EPHA2 (EPH receptor A2)
Diseases named in the same sentence as EPHA2 in open-access papers (continued):
Sharing a sentence is not in itself a finding about the gene and the disease.
glioma (93 papers, 2004 to 2026). A benign or malignant brain and spinal cord tumor that arises from glial cells (astrocytes, oligodendrocytes, ependymal cells). "Ephrin type-A receptor 2 (EphA2) is considered a glioma-associated antigen with expression in healthy tissue limited to some epithelial cells." (PMID 36303101, 2022). "EphA2 protein is overexpressed in gliomas and is associated with malignancy, thus it became a good molecular target in GBM." (PMID 33176788, 2020). "Glioma-associated antigen ephrin type A receptor 2 (EphA2) is highly expressed primarily in the GBM cells of the brain." (PMID 33224149, 2020). "Localised expression of EphA2 was found in VM-positive glioma in comparison to VM-negative glioma, which suggests an association of EphA2 with VM formation." (PMID 30914876, 2018). "This is consistent with an earlier study showing the failure of IV-delivered, second generation human EphA2-CAR T cells to cause any tumor regression of human glioma orthotopically implanted in the brain of SCID (severe combined immunodeficiency) mice." (PMID 29712574, 2018). "Ephrin A1 binding to EphA2 causes dephosphorylation of EphA2 Ser897 and reduces migration capacity in glioma- and prostate cancer cells." (PMID 27533087, 2016). "Supporting this notion, immunohistochemical examination of human glioma specimens with an antibody against the phospho-S897 revealed that activation of Akt-EphA2 signaling is associated with malignant progression." (PMID 22916121, 2012). "Overexpression of EphA2 in breast epithelial cells induced morphological transformation, while in prostate cancer and glioma cell lines, elevated EphA2 expression caused increased chemotactic cell migration and invasion." (PMID 22916121, 2012). "We hereby define these three antigens (mgp100, TRP-2 and EphA2) as the glioma-associated antigens (GAAs) in the GL261 glioma cells." (PMID 17295916, 2007). "Moreover, elevated EPHA2 expression has been associated with increased tumor sizes in gastric adenocarcinoma and gliomas." (PMID 35626181, 2022). "In cancer cells, including PTEN deficient prostate cancer cells and glioma cells, ephrin-dependent EphA2 activation led to rapid dephosphorylation of Akt at T308 and S473 residues leading in some cases to mTORC1 inactivation and decreased cell growth and migration." (PMID 33572284, 2021). "Besides, in glioma-derived cell lines, a decrease in miR-141 is associated with an increase in EPHA2 and an increase in VM." (PMID 32175277, 2020). "Furthermore, binding of Ephrin A1 to EphA2 has in prostate cancer and glioma cells been demonstrated to block proliferation- and invasion signaling mediated by EphA2, an effect in part caused by inhibition of EphA2 Ser897 phosphorylation." (PMID 27533087, 2016). "In gliomas, particularly glioblastoma multiforme, overexpression of EphA2 and EphA3 correlates with higher tumor grade and increased invasiveness." (PMID 41200151, 2025). "Conversely, the knockdown of EPHA2 in glioma stem cells downregulated extracellular matrix (ECM)-related protein expression of MMPs, which inhibited VM formation in vitro and in vivo." (PMID 40869298, 2025). "Examples of TAAs targeted in pediatric glioma vaccines include the cytomegalovirus (CMV) pp65 antigen and glioma-associated antigens (GAAs) such as EphA2, IL13RA2, and Survivin." (PMID 41441679, 2025). "EphA2 is overexpressed in approximately 67% of glioma patients and is inversely correlated with overall survival, making it a key prognostic marker alongside VEGF and vWF." (PMID 41200151, 2025). "Immunohistochemical studies in glioma patients showed significantly higher expression of EphA2 (90.91%) and MMP-2 (86.36%) in high-grade tumors compared to low-grade cases." (PMID 41200151, 2025).
glioma (continued). "Erythropoietin-producing hepatocellular carcinoma A2 (EphA2) has emerged as an attractive target for the immunotherapy of GBM due to its overexpression in glioma while being minimally expressed i normal brain tissue." (PMID 38660136, 2024). "Regarding the Eph/ephrin signaling pathway exploitation in glioma therapeutic strategies, EPHA2 expression in high-grade gliomas makes it a potential therapeutic target, with compounds like Dasatinib showing promising results in patient survival." (PMID 38612645, 2024). "EPHA2 overexpression has also been shown to promote glioma cell migration in a ligand-independent manner, requiring its phosphorylation at serine 897 by Akt." (PMID 38612645, 2024). "Namely, EPHA2 expression in osteosarcoma has been correlated with invasive capacity and increased ephrin-B3 in glioma with more aggressive behavior." (PMID 38612645, 2024). "EPHA2 shows overexpression predominantly in pediatric CNS tumors and malignancies arising from bone and soft tissues, namely glioma, medulloblastoma cell lines, craniopharyngioma, NF2-deficient meningioma, Ewing sarcoma, and osteosarcoma." (PMID 38612645, 2024). "The expression of EphA2 in GSC spheres was confirmed through IF, and a correlation between TGFBI and EphA2 in human glioma specimens was observed via IHC staining." (PMID 39346536, 2024). "Since the survival of glioma-bearing mice was prolonged to a similar amount utilizing a 20-fold lower dose, this CAR demonstrated stronger anti-glioma action compared to the previous CAR vector targeting EphA2." (PMID 36721153, 2023). "Previous research revealed that EphA2-positive with EFNA1-negative glioma patients had shorter OS and PFS." (PMID 35945523, 2022). "It has been reported that CDH5 and erythropoietin-producing human hepatocellular receptor A2 (EphA2) are highly expressed in VM-positive glioma compared with VM-negative glioma, and their expression is required for VM formation." (PMID 36294763, 2022). "In glioblastoma, curcumin inhibits the formation of VM in human glioma U251 cells in a dose-dependent manner by down-regulating the protein and mRNA expression of EphA2, PI3K, and MMPs." (PMID 35248069, 2022). "To evaluate protein expression of PDGFRA and EPHA2 using clinical samples of glioma, we collected a 180-case glioma cohort (Cohort-180)." (PMID 35105853, 2022). "EPHA2 overexpression was observed to promote glioma stem cell (GSC) invasiveness in vivo and promote neurosphere formation in vitro." (PMID 34767259, 2022). "Recently, results of the first-in-human trial of intravenous administration EphA2-CAR-T in patients with high grade gliomas showed safety and transient clinical responses." (PMID 35603195, 2022). "Among the newly identified direct CIC target genes were EPHA2 and ID1, whose functions are linked to neurodevelopment and the tumourigenicity of in vivo glioma tumour models." (PMID 34767259, 2022). "Elevation of either EphA2 or EphA3 maintains glioma cells in a stem-like state by negatively regulating the MAPK/ERK pathway." (PMID 35448036, 2022). "Although activation of EphA2 following ephrin-A1 ligand interaction blocks chemotactic migration of glioma and prostate cancer cells, EphA2 upregulation induces cell migration through a ligand-independent mechanism." (PMID 36142306, 2022). "Recently, preclinical trials have been conducted targeting EphA2, which is highly expressed in gliomas, and anti-tumor effects have been observed through EphA2 suppression." (PMID 35448036, 2022). "EphA2 and EphA3 were highly expressed in the mesenchymal subtype glioma according to The Cancer Genome Atlas database." (PMID 35448036, 2022). "miR-124-3p also prevented cell proliferation, migration, and invasion in glioma via downregulation of Fra-2 and EphA2 in glioma." (PMID 36009075, 2022).
glioma (continued). "Survival analysis further suggested regulatory correlations: elevated expression of FAM18A-AS1 and miR-21 was associated with poor prognosis in low-grade glioma, and high expression of EGFR, WEE1, MAP2K3, JA1, and EPHA2 was associated with poor prognosis." (PMID 35296768, 2022). "Several preclinical studies showed potent anti-tumor activity of EphA2-directed CAR T cells against glioma-initiating cells in GBM xenograft and medulloblastoma mouse models." (PMID 36303101, 2022). "Studies have shown that AKT promotes the migration and invasion of glioma and prostate cancer cells by enhancing the phosphorylation of serine 897 of EPHA2." (PMID 33834064, 2021). "Miao and coworkers found that EphA2 S897 phosphorylation was present mainly in grade IV human glioma specimens, in regions enriched for pS473-Akt signal and invasive cells." (PMID 33572284, 2021). "This is consistent with the reported functions of ephrinA5 and EphA2, influencing proliferation, cell death, cell adhesion, and migration in diverse cancer types including glioma as well as during nervous system development." (PMID 33572758, 2021). "EphA2-directed CAR T cells have shown promising antiglioma activity in preclinical brain tumor models, and at least one clinical trial is accruing patients with recurrent gliomas to evaluate the safety and efficacy of EphA2-CAR T cells (NCT03423992)." (PMID 34760690, 2021). "EPHA2 expression was assessed in normal brain samples and glioma tissues through either IHC or RT-PCR in three studies." (PMID 34445116, 2021). "EphA2 CAR-Ts based on a humanized version of mAb EA2 (4H5) showed effective tumor cell killing of glioma cells both in vitro and in mouse xenografts, using multiple arrangements of costimulatory signaling domains." (PMID 32397088, 2020). "Preclinical studies demonstrated that a second generation EphA2-CAR T cell induced glioma xenograft tumor regression in vivo." (PMID 33176788, 2020). "PE‐Sun, which consists of three pathway‐extended genes, SIAE, NR4A1 and EPHA2, was evaluated in gliomas." (PMID 34766125, 2020). "Both activated Akt and Ser897-phosphorylated EphA2 are robustly expressed in GBM tissues, and an interaction of EphA2 with AKT is associated with the malignant progression of glioma." (PMID 32116702, 2020). "VE-cadherin and EphA2 are both over-expressed in glioma, playing vital roles in VM network formation by promoting extracellular matrix remodeling." (PMID 32116702, 2020). "EphA2 has successfully exhibited an anti-tumor activity as a target for CAR T therapy in a glioma xenograft model; however, data on the duration of remission are limited." (PMID 33224149, 2020). "Unlike ligand-mediated activation of EphA2, Akt-mediated phosphorylation of EphA2 on Ser897 has been reported to enhance cell migration and invasion in glioma cells." (PMID 32116702, 2020). "It has been shown that miR-141 overexpression inhibits VM formation through directly targeting EphA2 transcript, decreasing EphA2 protein levels in glioma and renal carcinomas." (PMID 31612116, 2019). "Since EphA2, EphA3 and ephrin-B2 were described to regulate tumor-propagating cell self-renewal, luciferase-transfected glioma stem cells (TPC8 cell line) were injected into mouse brains." (PMID 29849945, 2018). "This appears to hold true when the expression of EphA2 is found in a gradient with a higher expression in the higher grades of gliomas." (PMID 30914876, 2018). "The overexpression of EphA2 in GBM tissues promotes glioma cell migration and invasion, while its activation concurs to the renewal of cancer stem cells." (PMID 29849945, 2018). "Because EphA2 is known to mediate various key cellular processes, deregulated expressions of its gene and protein in glioma cells enable the promotion of tumour aggressiveness, invasion, and metastasis." (PMID 30914876, 2018).
glioma (continued). "The CARs in current studies are led by scFv against five antigens (HER-2, EGFRvIII, MUC-1, IL13Rα2, and EphA2), specific for antigens expressed on glioma cells and/or other solid tumors." (PMID 28993773, 2017). "Another study reported that miR-26b acts as a tumor suppressor in glioma and directly regulates EphA2 expression." (PMID 27078844, 2016). "This is in contrast to effects seen upon Ephrin A1 binding to EphA2 which has been reported to block EphA2 Ser897 and Akt Ser129, resulting in inhibition of migration/invasion of glioma and prostate cancer cells respectively." (PMID 27533087, 2016). "In vitro studies have demonstrated that EphA2 regulates gliomas, prostate tumor cell and also NSCLC cell migration." (PMID 27533087, 2016). "Endogenous tumor antigens have been identified in the GL261 glioma model, including EphA2 and Garc-1." (PMID 25933216, 2015). "In our results, LBH589 significantly blocked migration, invasion, and vasculogenic mimicry formation through the down-regulation of VEGF, MMP-2, EphA2 and up-regulation of E-cadherin in U251 glioma cells." (PMID 24418474, 2014). "Ectopic expression of miR-26b inhibited the proliferation, migration and invasion of human glioma cells, possibly via regulation of its downstream target, EphA2." (PMID 23374284, 2013). "IL-13 receptor alpha 2 (IL13Rα2), human epidermal growth factor receptor 2 (HER2), and Ephrin type A receptor 2 (EphA2) are all glioma-specific antigens that provide targets for CAR-based immunotherapy." (PMID 24273748, 2013). "Nine TAPPs from the glioma cells (Aim2, Art-4, EphA2, EZH2, Fosl1, PTH-rP, Sox11, Whsc2 and YKL-40) consistently exhibited increased mRNA presence (≥1.9-fold expression) after culturing the cells in hypoxia (1% O2)." (PMID 22957023, 2012). "Similar to other cell types tested, doxazosin also activated EphA2 on A172 glioma cells in a dose-dependent manner starting around 25 μM." (PMID 22916121, 2012). "Our study provides evidence that miR-26b acts as an anti-oncogene in glioma cells and is an important negative regulator of the EphA2 gene." (PMID 21264258, 2011). "This study helps us to better understand of the function of miR-26b and its regulation of EphA2 in glioma cells." (PMID 21264258, 2011). "It has been reported that vasculogenic mimicry (VM) exists in glioma and EphA2 is an important regulator for VM formation." (PMID 21264258, 2011). "In conclusion, this study demonstrates that miR-26b plays a key role in the malignancy of glioma cells by directly regulating EphA2 expression, which affects cell proliferation, migration and invasion." (PMID 21264258, 2011). "In the present work, U251 and C6 glioma cells, which express high levels of EphA2, formed classical VM networks on Matrigel." (PMID 21264258, 2011). "In order to evaluate the effects of miR-26b and EphA2 on VM formation in glioma cells, we performed VM network formation experiments in U87 MG, U251 and C6 cells." (PMID 21264258, 2011). "In our present study, we showed that high level expression of EphA2 was found in high grade glioma samples." (PMID 21264258, 2011). "Immunohistochemical analyses of paraffin-embedded specimens demonstrated a diffuse membranous, partially cytoplasmic staining pattern in glioma cells for both IL-13Rα2 and EphA2 (respectively)." (PMID 18093336, 2007). "Finally, human mesenchymal stem cells (hMSCs) engineered to secrete ephrinA1-PE38 selectively targeted EphA2-overexpressing glioma cells." (PMID 41200151, 2025). "More precisely, high levels of EPHA2 and EPHB4 expression could distinguish high-grade gliomas and NF2-deficient meningiomas." (PMID 38612645, 2024). "Moreover, IHC staining of human glioma samples confirmed a positive correlation between EphA2 and both SOX2 and CD133." (PMID 39346536, 2024).
glioma (continued). "Preclinical research has shown that EphA2-specific CAR-T cells can induce regression of glioma xenografts in severe combined immunodeficiency (SCID) mice and a significant survival advantage compared to untreated mice and mice treated with nontransduced T-cells." (PMID 38660136, 2024). "Towards this direction, EPHB4/ephrin-B2 signaling is explored as an antiangiogenic target, with anti-EPHB4 monoclonal antibodies successfully blocking EPHB4 signaling, while inhibition of EPHA2 and EPHB1-3 forward signaling in gliomas is associated with a dose-dependent reduction in cell invasion." (PMID 38612645, 2024). "Thus, the distribution feature of PDGFRA and EPHA2 implied that the two proteins were related with malignant phenotype of glioma." (PMID 35105853, 2022). "In human glioma, miR‐141 directly targets EphA2 and inhibits VM by controlling EphA2 expression." (PMID 35595748, 2022). "EphA2 further promotes infiltrative invasion of glioma stem cells." (PMID 33572758, 2021). "Ephrin-A1 expression was associated with lower grade gliomas, while patients with tumors positive for EPHA2 and negative for ephrin-A1 exhibited shorter OS and PFS." (PMID 34445116, 2021). "EPHA2 also contributes to human glioma stem cell formation and stemness marker SOX2 expression." (PMID 33436772, 2021). "Wu reported that miR-124-3p could impede malignant phenotypic manifestations within gliomas through inhibition of EphA2." (PMID 34689806, 2021). "Hypermethylation at CpG islands of promoter regions of many ephrins, including EfnA5, and Eph receptors have been demonstrated in acute lymphoblastic leukaemia and miRNAs, such as miR-210 and miR-26b, have been shown to downregulate the expression of EfnA1 in hepatic ischaemia and EphA2 in gliomas." (PMID 31988455, 2020). "VEGFR-2 plays a key role in vasculogenic mimicry formation, neovascularization, and tumor initiation by glioma stem-like cells, and EphA2 and its receptors are significantly involved in blood vessel formation and remodeling during the vascular development of cancers." (PMID 32599834, 2020). "A recent report showed that miR-141 may regulate VM formation by controlling EphA2 expression in human glioma." (PMID 32169087, 2020). "Taken together, the data indicate that EphA2 and VE-cadherin may promote VM formation in glioma through FAK phosphorylation and PI3K/Akt activation." (PMID 32116702, 2020). "In addition to targeting gliomas, EphA2-specifc T cells have also been developed and evaluated in NSCLC and esophageal squamous cell carcinoma (ESCC)." (PMID 32811512, 2020). "In human glioma tissues, EphA2 shows a heterogeneous staining pattern." (PMID 28752098, 2017). "Some suitable glioma-specific cell surface antigens have been identified, such as the EGF receptor (EGFR) and its variant EGFRvIII, HER2/neu, IL-13 receptor alpha chain 2, and the EPH receptor A2 (EphA2)." (PMID 27172791, 2016). "Similar to the findings for melanoma, both VE-cadherin and EphA2 are expressed at higher levels in VM-positive glioma than VM-negative glioma, and the expression of these genes correlates with the glioma grade and is known to be required for VM network formation." (PMID 26085929, 2015). "In addition, miR-26b inhibited the VM processes accompanied with the downregulation of EphA2 proteins, which revealed that EphA2 was correlated with the capability of VM formation in gliomas." (PMID 25202424, 2014). "This was first performed using the U373 glioma cell line engineered to overexpress EphA2." (PMID 22916121, 2012). "Many of the TAPP were not differentially expressed in the hypoxic cells but nine TAPPs from the glioma cells (Aim2, Art-4, EphA2, EZH2, Fosl1, PTH-rP, Sox11, Whsc2 and YKL-40) consistently exhibited increased mRNA presence after culturing the cells in response to hypoxia." (PMID 22957023, 2012). "Additionally, we further confirmed that miR-26b is an important regulator of EphA2, and there was an interaction between miR-26b and EphA2 in glioma cells." (PMID 21264258, 2011).